SIRT1 (sirtuin 1)
Diseases named in the same sentence as SIRT1 in open-access papers (continued):
Sharing a sentence is not in itself a finding about the gene and the disease.
Stroke (continued). "In the microvasculature, circ-HIPK3 sponges miR-148b-3p, downregulating cyclin-dependent kinase 5 (CDK5) and CDK5 receptor 1 expression, which ultimately upregulates SIRT1 to promote post-stroke BMEC survival and mitochondrial function." (PMID 39598406, 2024). "The importance of SIRT1 as a molecular target in aging-related diseases, such as diabetic retinopathy and stroke, is underscored, along with the need for more clinical evidence to support SIRT1 modulation in the microcirculation." (PMID 39598406, 2024). "One such study indicated that acute‐phase exercise post‐stroke increases SIRT1 expression, which regulates ER stress pathways involved in neuroprotection." (PMID 39328024, 2024). "Further comparative mechanistic and long-term studies in post-stroke aged male and female brains investigating the effects of Sirt1 overexpression, activation, and inactivation are warranted." (PMID 37191419, 2023). "Sirt1 is activated after the onset of stroke and can regulate multiple signaling pathways to affect oxidative stress, further modulating the pathological process of stroke." (PMID 37622049, 2023). "In the present study we assessed the role of miR-200c on injury, Sirt1, and bioenergetic and neuroinflammatory markers in aged male and female mice after experimental stroke." (PMID 37191419, 2023). "Further studies are needed to thoroughly understand the regulatory effect of Sirt1 on autophagy, which is of great significance for the prevention and treatment of stroke." (PMID 37622049, 2023). "Sirtuin 1 (Sirt1) has been shown to play a critical role in stroke, neurodegenerative diseases and aging." (PMID 36725745, 2023). "Sirt1 is a gatekeeper for m6A methylases and changes in m6A methylation of mRNAs after experimental stroke have been described in young adult rodents." (PMID 37191419, 2023). "In a mouse model of MCAO-induced stroke, a decrease in the level of SIRT1 protein increased ROS expression." (PMID 37627275, 2023). "We previously demonstrated that inhibition of miR-200c was protective against stroke in young adult male mice by augmenting sirtuin-1 (Sirt1)." (PMID 37191419, 2023). "Activation of Sirt1 exerted its neuroprotection by inhibiting cellular pyroptosis after stroke via the ROS-TRFA6 signaling pathway." (PMID 37622049, 2023). "Activation of SIRT1 has also been shown to be a promising therapeutic target for protective strategies for stroke." (PMID 36466801, 2022). "There was a dose-dependent increase in antioxidant activity and suppression of apoptosis with Pic, as well as upregulation of Sirt1/FoxO1 signaling in stroke." (PMID 36105479, 2022). "It proved that Pic potentially exerts neuroprotective effects through upregulation of Sirt1/FoxO1 signaling in stroke." (PMID 36105479, 2022). "We believe that our work will be helpful to further understand the critical role of the SIRT1 signaling pathway and will provide novel therapeutic potential for stroke treatment." (PMID 36105479, 2022). "This review summarized the potential mechanisms and natural products used in stroke by which Sirt1 protects against stroke through antioxidative and anti-inflammatory effects." (PMID 36105479, 2022). "Our results demonstrate that the loss of SIRT1 causes a sequential chain of mitochondrial dysfunction, defective autophagy, and neuronal apoptosis after IRI in the preclinical stroke models." (PMID 35528522, 2022). "This section summarizes the critical signaling pathway proteins in the process of SIRT1-mediated antioxidation in stroke." (PMID 36105479, 2022). "SIRT1 is activated after the onset of stroke and can regulate multiple signaling pathways to affect oxidative stress, further regulating the pathological process of stroke." (PMID 36105479, 2022). "Two deacetylases, Sirt1 and Sirt3, are shown to control the blood–brain barrier integrity after stroke." (PMID 36361891, 2022).
Stroke (continued). "We observed decreased SIRT1 expression in the brains of experimental rats following CI and increased SIRT1 expression in patients with stroke." (PMID 33737560, 2021). "Reduced expression of the SIRT1 gene and reduced SIRT1 activity, resulting in skeletal muscle atrophy, have been demonstrated in post-stroke animal models; similarly, attenuation of muscle atrophy was found when SIRT1 is overexpressed." (PMID 35002937, 2021). "Emerging evidence supports that genetic and pharmacological manipulation of SIRT1 modulates stroke outcome." (PMID 33737560, 2021). "We used an ischemia/reperfusion rat model to define the effect of exercise postconditioning after stroke and determine the relationship between SIRT1 and ROS/ER stress." (PMID 33664650, 2021). "We demonstrate that SirT1 overexpression decreased the stroke‐induced ZNF216 gene expression in skeletal muscle." (PMID 32676579, 2020). "The objective of this study is to determine the molecular mechanisms by which stroke induces muscle atrophy and the role of SirT1 in this process." (PMID 32676579, 2020). "This suggests that stroke negatively regulates SirT1 both at the transcriptional and post‐transcriptional levels." (PMID 32676579, 2020). "In the present study, we also showed that while stroke inhibits SirT1 activity, it increases PARP activity in skeletal muscle." (PMID 32676579, 2020). "Muscle‐specific SirT1 gain‐of‐function mice are resistant to stroke‐induced muscle atrophy and this protective effect requires its deacetylase activity." (PMID 32676579, 2020). "Resveratrol is not a specific activator of SIRT1, but accumulating findings suggest that resveratrol exerts neuroprotection via activation of SIRT1 in neurodegenerative diseases and stroke." (PMID 33381265, 2020). "To determine the regulation of the SirT1 gene in skeletal muscle in response to stroke, we measured SirT1 mRNA and protein levels in the paralytic tibialis anterior (PTA) muscle of MCAO mice and corrsponding tibialis anterior (CTA) muscle of sham mice." (PMID 32676579, 2020). "In contrast, stroke has a minimal effect on signaling for muscle atrophy in SirT1+/+ mice, suggesting that SirT1 offsets the stroke‐induced muscle atrophy program." (PMID 32676579, 2020). "In contrast, overexpression of SirT1 in skeletal muscle prevented the elevation of stroke‐induced PARP activity." (PMID 32676579, 2020). "Using a preclinical mouse model of cerebral ischemic stroke, we show that stroke robustly induced atrophy and significantly decreased SirT1 gene expression in the PTA (paralytic tibialis anterior) muscle." (PMID 32676579, 2020). "Epigenetic roles of sirtuins, predominantly Sirt1 and 3, are described in stroke injury via acetylation/deacetylation of targets." (PMID 31543756, 2019). "Altogether, Sirt1 is a promising therapeutic target for ischemic stroke for attenuating ischemic stress and improving stroke outcome." (PMID 30519156, 2018). "These evidences suggested that SIRT1/VEGF pathway plays a critical role in angiogenesis during stroke recovery." (PMID 30564092, 2018). "For example, neuronal SIRT1 and Nrf2 function in astrocytes are required for resveratrol-induced protection from stroke in mice." (PMID 29440987, 2018). "A previous work by a number of other laboratories has also established that RSV potentiates SIRT1 activity and provides neuroprotection in recurrent stroke models, stress resistance, and prosurvival effects." (PMID 29081884, 2017). "The effects of telomerase and Sirt1 are exciting new areas of translational stroke and aging research." (PMID 22132330, 2011). "Resveratrol, a chemical found in red wine, has been shown to increase activity of Sirt1 and attenuate inflammatory response in animal models of stroke." (PMID 22132330, 2011). "Another protein that prevents apoptosis in stroke, whose deacetylation is mediated by SIRT1, is PGC-1α." (PMID 21910904, 2011).
Stroke (continued). "The SIRT1–NF-κB pathway has been shown to alleviate inflammasome signaling and cellular apoptosis in the intra-arterial mesenchymal stem cell therapy following stroke." (PMID 40724883, 2025). "In SIRT3 knockout mice post-stroke, neuroprotection occurred through a compensatory increase in SIRT1 levels, independent of the loss of SIRT3." (PMID 40356977, 2025). "The role of SIRT1-mediated autophagy in stroke was also confirmed in patients with stroke." (PMID 40724883, 2025). "Therefore, in parallel we also measured m6A methylation of SIRT1 mRNA in aged males and females in response to experimental stroke." (PMID 37191419, 2023). "As a member of the sirtuin family, SIRT1 regulated a broad physiological process, covering apoptosis and inflammatory reaction, and may be protective factors for stroke." (PMID 38020537, 2023). "Pre-clinical studies in young adult male animals support the hypothesis that activation of Sirt1 can be protective against stroke, however more recent evidence indicates any protective effect is both age- and sex-dependent." (PMID 37191419, 2023). "There is bidirectional regulation of autophagy by Sirt1 in stroke." (PMID 37622049, 2023). "In recent years, SIRT1 has been recognized as particularly important in the pathogenesis of stroke." (PMID 36105479, 2022). "This section is aimed at summarizing the natural products acting on SIRT1 for stroke treatment." (PMID 36105479, 2022). "Sprague Dawley (SD) rats were divided into 4 groups: sham operation group (Sham group, n = 5), poststroke central pain group (CPSP group, n = 5), poststroke central pain + acupuncture group (AP group, n = 5), central pain after stroke + acupuncture + SIRT1 inhibitor EX527 group (EX527 group, n = 5)." (PMID 36059399, 2022). "In addition, many other drugs have been shown to exert neuroprotective effects by upregulating SIRT1-dependent PGC-1α expression to induce antioxidation in stroke." (PMID 36105479, 2022). "Reducing ROS and neuroinflammation by targeting SIRT1 may represent a promising therapeutic target for stroke." (PMID 36105479, 2022). "Possible antioxidant and anti-inflammatory effects downstream of AMPK and SIRT1 activation may explain the neutral impact of SGLT2i use on stroke." (PMID 35658864, 2022). "Therefore, we conducted the present review to summarize the mechanisms of SIRT1-mediated oxidative stress and neuroinflammation in stroke." (PMID 36105479, 2022). "In addition, SIRT1 plays an important role in stroke pathogenesis via its ability to modulate oxidative stress and inflammation." (PMID 36105479, 2022). "Although this study found that the improvement of stroke by acupuncture was related to the upregulation of SIRT1 expression levels in brain tissue and the significant downregulation of the expression levels of NLRP3 and IL-18, the specific in-depth mechanisms were not further studied." (PMID 36059399, 2022). "Targeting SIRT1 to reduce ROS and neuroinflammation might represent an emerging therapeutic target for stroke." (PMID 36105479, 2022). "The following search terms were used: SIRT1, oxidation, neuroinflammation, and stroke." (PMID 36105479, 2022). "In addition, we discuss the potential mechanisms and natural compounds used for stroke treatment by which SIRT1 protects against stroke through antioxidative and anti-inflammatory effects." (PMID 36105479, 2022). "In addition, we provide a comprehensive introduction to the effect of compounds and natural drugs on SIRT1 signaling related to oxidative stress and neuroinflammation in stroke." (PMID 36105479, 2022). "Furthermore, post-stroke exercise increased SIRT1 expression and had an inverse relationship with ROS levels." (PMID 33664650, 2021). "However, the precise mechanism by which exercise postconditioning affects the SIRT1/ER stress signal after stroke remains undetermined." (PMID 33664650, 2021).
Stroke (continued). "Additionally, both PostE groups saw significant increases in SIRT1 expression.In this study, both mild and intense PostE levels induced neuroprotection after stroke through SIRT1 and ROS/ER stress pathway." (PMID 33664650, 2021). "NAD+-dependent deacetylases (SIRT), a gene family, are related to many diseases including IS, and quercetin could alleviate the condition of stroke patients by activating SIRT1." (PMID 34194527, 2021). "Inhibition of neuroprotective SIRT1 usually worsens stroke outcome." (PMID 34680562, 2021). "We hypothesize that stroke causes muscle atrophy, in part, by inhibiting SirT1 function and SirT1 rescue preserves post‐stroke muscle mass by blocking the expression of key players of UPS." (PMID 32676579, 2020). "Moreover, stroke inhibits SirT1 gene transcription as SirT1 mRNA and protein levels were declined in PTA muscle." (PMID 32676579, 2020). "Overall, it was concluded that SIRT3 KO mice show neuroprotection by a compensatory rise in SIRT1 rather than the loss of SIRT3 after stroke." (PMID 32380741, 2020). "We also found that stroke inhibits SirT1 gene expression and its activity in skeletal muscle." (PMID 32676579, 2020). "Interestingly, SirT1 rescue in post‐stroke muscle, dramatically reduced atrophy and the expression of MuRF1, Atrogin1 and ZNF216 genes." (PMID 32676579, 2020). "As stroke inhibits the expression of SirT1, which has been shown to block muscle atrophy, we rationalized that preserving SirT1 function may prevent post‐stroke muscle atrophy." (PMID 32676579, 2020). "Interestingly, we found a role for SirT1 in the regulation of stroke‐induced Atrogin‐1 and MuRF‐1 in post‐stroke muscle." (PMID 32676579, 2020). "Although the role of sirtuins in NVU and BBB recovery after stroke is still largely unexplored, emerging data on sirtuin effects on the BBB, endothelial cells, and stroke, put these molecules, and particularly Sirt1, as important targets for epigenetic modification of NVU and BBB in stroke recovery." (PMID 31543756, 2019). "Resveratrol, a potent activator of Sirt1, has neuroprotective effects after stroke (enhancing neurite outgrowth and synaptogenesis) and vascular protective effects, reducing the chance of recurrent stroke." (PMID 31543756, 2019). "The neuroprotective effects of SIRT1 in stroke have been reported." (PMID 30564092, 2018). "Although it is still a controversy whether Sirt1 could improve stroke outcome, there have been plenty of studies indicating the potential therapeutic value of Sirt1 for ischemic stroke." (PMID 30519156, 2018). "Sal-B can protect against acute ethanol-induced liver injury via SIRT1 activation and attenuate apoptosis and inflammation via activating SIRT1 in experimental stroke rats, indicating that the neuroprotection of Sal-B is related to the inhibition of SIRT1/NF-κB pathway." (PMID 29498696, 2018). "We explored BHD targets the SIRT1/VEGF signal pathway in angiogenesis after stroke." (PMID 30564092, 2018). "In another study, nicotinamide, a compound that inhibits SIRT1 action, showed neuroprotection against ischemic injury, implying that SIRT1 might have a detrimental effect against stroke." (PMID 23888142, 2013). "SIRT1 and its inhibitory role on NFκB could have a lot to do with the lower transcription levels of inflammatory markers seen after stroke in CR organisms." (PMID 21910904, 2011). "Thus, SIRT1 may mediate the beneficial effects of MSCs in stroke by regulating inflammasome signaling." (PMID 40724883, 2025). "By activating the forkhead box O (FoxO) and SIRT1/FoxO1 signaling pathways, exercise could reduce cell death and neural loss, increase brain-derived neurotrophic factor (BDNF) production, and promote neuroplasticity and functional recovery after the stroke." (PMID 38992073, 2024). "However, whether Sirt1 can regulate microglial activation after stroke and whether this would involve the Shh signaling pathway remains not quite clear." (PMID 36725745, 2023).
Stroke (continued). "However, the direct regulatory effect of Sirt1 on autophagy in stroke remains unclear and needs to be confirmed by further studies." (PMID 37622049, 2023). "Sirt1 has been shown to exert age-dependent effects on injury from experimental stroke in rats, however whether Sirt1 levels are associated with differential outcomes in stroke between sexes in the aged brain has never been assessed." (PMID 37191419, 2023). "Moreover, a study of OGD/R revealed that the serine/threonine-specific protein kinase (CaMKK) alleviated ischemic brain damage by protecting the microvascular system and decreasing the infiltration of proinflammatory factors in a SIRT1-dependent manner after stroke." (PMID 36507335, 2022). "In addition, PGC1α is important for SIRT1 to improve stroke-related conditions." (PMID 34658877, 2021). "The relationship between various exercise intensities and SIRT1/ER stress levels may help elucidate the mechanism of exercise-induced neuroprotection after ischemic stroke and guide efforts to optimize exercise intensity in postconditioning after stroke." (PMID 33664650, 2021). "Our findings could be a basis to further clarify the participation of SIRT1 in ER stress in stroke." (PMID 33664650, 2021). "Clinically used selective inhibitor SIRT1 Selisistat, also known as EX-527, reduces the volume of ischemic brain infarction and improves survival, but does not reduce neurological deficits associated with stroke." (PMID 34680562, 2021). "Therefore, Sirt1 activation after a stroke may be a strategy to prevent subsequent neurodegeneration by inhibition of both neuronal and endothelial amyloidogenic pathways as well as HMGB1-mediated neuroinflammation." (PMID 33318474, 2020). "Therefore, Sirt1-dependent endothelial HMGB1 secretion in patients following a stroke might be a target to prevent progression to AD, although further in vivo and clinical studies are needed to confirm this." (PMID 33318474, 2020). "However, it has not previously been explored whether MCPs regulate nuclear translocation of β-Catenin via SIRT1 to promote differentiation of NSCs after stroke." (PMID 33198798, 2020). "Therefore, in the present study, we aim to determine whether MCPs could improve NSC differentiation and to further explore whether SIRT1/β-catenin axis plays roles in post-stroke neurogenesis." (PMID 33198798, 2020). "However, the answer to whether upregulation of Sirt1 improves the outcome of stroke is still a controversy." (PMID 30519156, 2018). "Therefore, SIRT1 may be a key protective protein in stroke that can be epigenetically regulated." (PMID 40724883, 2025). "Increased immunoreactivity of SIRT1, Beclin 1, ATG7, LC3-I/II, and cleaved caspase-3 was also noted in stroke brains." (PMID 40724883, 2025). "Another aspect of the epigenetics concerning the sirtuin/stroke connection is the action of the lncRNA SNHG8, which sponges miR-449c-5p and regulates the SIRT1/FOXO1 pathway to inhibit microglia activation and decrease BBB permeability in ischemic stroke." (PMID 40724883, 2025). "In the context of obesity-induced diabetes, a significant risk factor for stroke, research has highlighted the interaction between sirtuin (Sirt1) and NOX in stroke recovery." (PMID 39334724, 2024). "Females had greater baseline miR-200c expression and a greater increase in miR-200c in response to stroke, while pre-MCAO levels of m6A SIRT1 was greater in females." (PMID 37191419, 2023). "Resveratrol, a specific Sirt1 agonist, performed the positive effect on the inhibition of NLRP3 inflammasome and neuroprotection after embolic stroke." (PMID 37622049, 2023). "Some specific lysine residues in MAPT can be deacetylated by SIRT1, which means that a pivotal role is played by SIRT1/MAPT pathway during stroke recovery." (PMID 36105479, 2022). "In an in vitro stroke model of the BBB, comprising of human brain microvascular endothelial cells and astrocytes, Sirt1 suppression reduced BBB permeability." (PMID 36361891, 2022).